MIF (macrophage migration inhibitory factor)
Diseases named in the same sentence as MIF in open-access papers (continued):
Sharing a sentence is not in itself a finding about the gene and the disease.
pancreatic cancer (continued). "In the pancreatic cancer lymph node tissue, the MIF_CD74 ligand-receptor pair played an important communication role, primarily in the communication among acinar cells." (PMID 39156890, 2024). "Elevated MIF levels in pancreatic carcinoma tissue are correlated with worse prognosis, and studies have consistently demonstrated MIF and DDT’s role in disease progression via driving proliferation, invasion, and anti-apoptotic processes." (PMID 38732068, 2024). "In contrast, MIF is positively regulated by miRNA-451 (colorectal carcinoma) and miRNA-301b (pancreatic carcinoma)." (PMID 38732068, 2024). "In pancreatic cancer, evidence exists for changes toward a typical pro-inflammatory cytokine expression: in tissues higher MIF, IL-8, and CXCR-4 expression and reduced HLA-DR expression, and in serum higher IL-6 and IL-10 levels." (PMID 35034144, 2022). "Increasing data indicated that MIF promoted migration and invasion of cancer cells, so to investigate the effects of MIF on the invasive phenotype of pancreatic cancer cells, we sought to determine the impact of altered expression of MIF on cellular mobility." (PMID 36703790, 2022). "The results showed that MIF was generally and differentially expressed in these five pancreatic cancer cell lines." (PMID 36703790, 2022). "To detect the expression of MIF in most used pancreatic cancer cell lines and its relationship with hypoxia in vitro, then we examined MIF protein expression in a panel of pancreatic cancer cell lines using western blotting." (PMID 36703790, 2022). "It has been demonstrated that macrophage migration inhibitory factor (MIF) is highly expressed in pancreatic cancer-derived exosomes." (PMID 35159011, 2022). "MIF is a cytokine that is known to be secreted in high concentrations by pancreatic tumors that can act directly on myeloid cells." (PMID 35140221, 2022). "The levels of MIF expression vary in pancreatic cancer cell lines with high over-expression in PT-45, CFPAC-1, PaCa2, and Capan-1 cells (Ct < 6.5)." (PMID 33776775, 2021). "Later, it was found that the generation of PMNs in the liver is promoted by Kupffer cells taking up pancreatic cancer-derived exosomes carrying MIF." (PMID 33738282, 2021). "A recent study found that recombinant MIF treatment significantly enhanced tumor growth via promoting angiogenesis in a hamster pancreatic cancer model induced by subcutaneous inoculation with HapT1 cells." (PMID 33776775, 2021). "Exosomes secreted from breast or pancreatic cancers contribute to the formation of metastatic niche carrying telomerase or macrophage migration inhibitory factor (MIF) to the TME." (PMID 33669294, 2021). "In pancreatic cancer, MIF enhances the proliferation and invasion of tumor cells, resulting in increased tumor growth and metastasis in vivo." (PMID 33776775, 2021). "For instance, macrophage migration inhibitory factor (MIF) containing EVs from pancreatic cancer cells were shown to selectively target and activate Kupfer cells (KCs) in the liver, resulting in increased secretion of TGF-β." (PMID 34656117, 2021). "We expect to provide insights into clinical translation of MIF antagonism as a strategy for treating acute pancreatitis and pancreatic cancer." (PMID 33776775, 2021). "Second, macrophage MIF, an important component of pancreatic cancer exosomes, promotes fibrotic cytokine secretion after fusion with Kupffer cells, activates fibrotic pathways, and ultimately establishes a pro-inflammatory environment for metastasis." (PMID 34485600, 2021). "Macrophage migration inhibitory factor (MIF) is highly expressed in pancreatic cancer cell-derived exosomes." (PMID 34616739, 2021).
pancreatic cancer (continued). "In a mouse model of pancreatic cancer, liver-resident macrophages that uptake tumor-derived exosomes containing high macrophage migration inhibitory factor (MIF) showed an elevated TGFβ secretion." (PMID 34884995, 2021). "For example, pancreatic cancer‐derived exosomes contain high amount of macrophage migration inhibitory factor (MIF), which recruits macrophages to induce the formation of PMN in the liver and promote liver metastasis." (PMID 32449597, 2020). "Significant elevation in MIF positive staining was observed in both para-carcinoma and pancreatic cancer tissue samples as compared to normal tissue." (PMID 32317702, 2020). "We next investigated the biological significantce of the inhibition of MIF activity in PANC-1 pancreatic cancer cells using the MIF inhibitor ISO-1." (PMID 32317702, 2020). "Increased levels of MIF have been reported in many cancer types including pancreatic cancer, hepatocellular cancer or head and neck cancer." (PMID 32493768, 2020). "We first reaffirmed the involvement of MIF in pancreatic cancer tumourigenesis by examining the expression of MIF in human pancreatic cancer tissue samples, in para-carcinoma tissues and in normal tissue." (PMID 32317702, 2020). "For example, in a well-characterized model of pancreatic cancer, tumors were found to secrete exosomes containing macrophage migration inhibitory factor (MIF), which induces TGFβ signaling in Kupffer cells in the liver." (PMID 32547552, 2020). "Semi-quantitative measurement based on the integrated optical density (IOD) of staining intensity, showed that the expression of MIF was elevated 10-folds in pancreatic cancer tissues as compared to normal tissues." (PMID 32317702, 2020). "Pancreatic cancer-derived exosomes contain macrophage migration inhibitory factor (MIF) that induces TGF-β secretion by Kupffer cells in the liver, which stimulates an enhanced fibronectin deposition by neighbouring hepatic stellate cells." (PMID 33037194, 2020). "Our finding that MIF expression is substantially elevated in human para-carcinoma and pancreatic cancer tissues provides further evidence for the importance of MIF in pancreatic tumorigenesis." (PMID 32317702, 2020). "Study showed that pancreatic cancer cell-derived exosomes initiated PMN formation in the liver through MIF." (PMID 30792719, 2019). "Pancreatic tumor-derived exosomes expressing MIF promote TGF-β secretion from Kupffer cells, which stimulates fibronectin secretion from hepatic stellate cells and recruits myeloid CD11b+ cells to the PMN in the liver." (PMID 30792719, 2019). "Taken together, the data presented in this study have unraveled multiple information regarding MaMIF, and indicate the importance of hamster as a model to investigate questions related to the role of MIF in pancreatic cancer progression." (PMID 31664114, 2019). "Pancreatic cancer cells overexpress MIF and are believed to be the major contributor to the overall MIF level in the pancreatic tumor microenvironment." (PMID 31664114, 2019). "Pancreatic cancer cell-derived exosomes initiate PMN formation in the liver through macrophage migration inhibitory factor (MIF)." (PMID 30792719, 2019). "At that particular time, due to the unavailability of information and reagents for Mesocricetus auratus MIF (MaMIF), we were unable to investigate the function of this molecule in the hamster model of pancreatic cancer." (PMID 31664114, 2019). "Macrophage migration inhibitory factor (MIF) is highly expressed in pancreatic cancer-derived exosomes, and its inhibitory effect can prevent the formation and metastasis of pancreatic cancer before the formation of liver metastasis." (PMID 31487880, 2019). "There are also reports of pancreatic cancer exosome-mediated transfer of macrophage migration inhibitory factor (MIF) to liver Kupffer cells, subsequent to increasing TGF-β and fibronectin production, thus aiding tissue remodeling and future tumor metastasis." (PMID 30895170, 2019).
pancreatic cancer (continued). "In pancreatic cancer patients, the tumor tissues and circulating blood have a higher level of MIF than in healthy subjects." (PMID 31664114, 2019). "Together, the effect of MaMIF in promoting the growth of HapT1 tumors corroborates and confirms the pro-tumorigenic role of MIF in pancreatic cancer progression." (PMID 31664114, 2019). "GPC1-positive exosomes have been employed to detect pancreatic cancer, while circulating exosomal macrophage migration inhibitory factor (MIF) was able to predict liver metastasis onset." (PMID 31537986, 2019). "In pancreatic cancer, MIF is an important downstream regulator of fibrosis that culminates in the recruitment of TAMs favoring metastasis." (PMID 29875777, 2018). "Undoubtedly, exosomes impact pancreatic cancer metastasis in ways that reach beyond MIF-dependent interactions." (PMID 29903049, 2018). "Macrophage migration inhibitory factor in pancreatic cancer-derived exosomes can prime the liver for metastasis." (PMID 29725020, 2018). "For instance, pancreatic cancer-derived macrophage migration inhibitory factor (MIF)+ exosomes facilitate liver metastasis, and exosomal integrin α6β4 and α6β1 are associated with lung metastasis." (PMID 28178689, 2017). "We initially evaluated the possibility that this was due in part to the influence of MUC1 on levels of c-Jun in two MUC1 overexpressing human pancreatic tumor cell lines, S2013.MIF and Panc1.MUC1, as compared to their low-expressing counterparts." (PMID 27220889, 2016). "MIF can be used as a prognostic marker in the development of liver metastasis in patients with pancreatic cancer." (PMID 28105072, 2016). "The macrophage migration inhibitory factor (MIF) was highly expressed by the exosomes of the pancreatic tumour and its blockage prevents the premetastatic niche formation and subsequently metastasis." (PMID 28105072, 2016). "Although first described as an immune cell product, a much higher MIF level was found in kinds of human cancer and cancer-prone inflammatory diseases, including chronic pancreatitis and pancreatic cancer." (PMID 24708788, 2014). "Quantitative RT-PCR on RNA isolated from human pancreatic cancer tissues showed higher MIF expression in patients with new-onset DM compared with patients with long-term DM or those without DM." (PMID 24708788, 2014). "The impact of MIF in cancer cell proliferation was also shown by another group that inhibited MIF production in pancreatic cancer cells using siRNAs and found not only a decrease in proliferation, but also the induction of apoptosis of these cells." (PMID 24887129, 2014). "Our study is one of the few researches on the diabetogenic ability of pancreatic cancer cells, and further studies to investigate the role of MIF as well as identify other candidate mediators of PCDM are needed." (PMID 24708788, 2014). "In comparison, pancreatic cancer specimens showed a strong positive MIF staining; MIF expression was found not only in cancer cells but also neighboring ducts, acini, and islets." (PMID 24708788, 2014). "MIF expression was significantly increased in pancreatic cancer tissues compared with chronic pancreatitis or normal pancreas specimens." (PMID 24708788, 2014). "Because MIF was overexpressed in pancreatic cancer cells, we used MIF shRNA to knock down MIF in PANC-1 and Capan-2 cells." (PMID 24708788, 2014). "Mechanistic analyses revealed that MIF overexpression increased protein levels in pancreatic cancer cell lines, consistent with the features of EMT." (PMID 24084722, 2013). "Similarly, in other cancers like pancreatic cancer, MIF has been shown to enhance invasion and metastasis." (PMID 40835826, 2025). "Investigations have found that MIF also played role in pancreatic cancer development." (PMID 41159021, 2025).
pancreatic cancer (continued). "Furthermore, in another investigation, it was reported that tautomerase inhibitor, IPG1576 (inhibitor for tautomerase activity of MIF) resulted in decreased exosome-induced MDSCs activation and differentiation and pancreatic tumor growth." (PMID 41159021, 2025). "There are several specific exosomes that can contribute to liver metastasis in pancreatic cancer via forming an inflammatory and immunosuppressive microenvironment in the liver, e.g., macrophage migration inhibitory factor (MIF), Integrin ITG αvβ5, Netrin-1, Lin28B and CD44." (PMID 38954230, 2024). "MIF acted as an autocrine growth factor that promoted pancreatic cancer cell proliferation." (PMID 36042480, 2022). "However, in PDAC with high MIF expression, the expression level of nr3c2 was relatively low, which indirectly proved that MIF was positively correlated with the mortality and invasion ability of pancreatic cancer cells." (PMID 34485124, 2021). "We found high expression of MIF in pancreatic cancer tissues." (PMID 32317702, 2020). "Moreover, the presence of a substantially higher number of Ki67-positive cells (p < 0.0001) in the tumors of MaMIF-injected animals than PBS injected animals corroborates the observed pro-tumorigenic effect of exogenous MIF on pancreatic tumors in vivo." (PMID 31664114, 2019). "Importantly, the current study provides convincing experimental evidence which suggests that the hamster model of pancreatic cancer can be reliably used to investigate MIF related questions in pancreatic cancer." (PMID 31664114, 2019). "Hence, while designing MIF-targeted therapy in pancreatic cancer, all the possible sources of MIF that can affect overall tumor growth need to be taken into consideration." (PMID 31664114, 2019). "Hence, the major objectives of this study were to characterize the structure and function of Mesocricetus auratus MIF (MaMIF) and finally evaluate its effect on pancreatic tumor growth in vivo." (PMID 31664114, 2019). "Hence, in the current study, our major objective was to characterize the MaMIF protein and evaluate the effect of exogenous MIF on the growth of pancreatic tumor in a syngeneic model of hamster pancreatic cancer." (PMID 31664114, 2019). "Macrophage migration inhibitory factor (MIF) was found to promote hepatic metastasis of cancers, and could be used as an early stage diagnostic marker for pancreatic cancer hepatic metastasis." (PMID 28851367, 2017). "In this study, we aimed to demonstrate the biological relevance of MIF in pancreatic cancer induced β-cell dysfunction, and to identify whether it could serve as a potential biomarker of PC associated diabetes that can distinguish it from type 2 diabetes." (PMID 24708788, 2014). "Besides, previous research indicated that MIF may promote the development of pancreatic cancer by forming a positive feedback loop with HIF-1α42." (PMID 41210694, 2025). "Moreover, a better understanding of the mechanisms through which circulating MIF can promote pancreatic tumor progression might provide a rationale to design an effective therapeutic strategy against this deadly disease." (PMID 31664114, 2019). "Consistent with our study, several studies have reported increased CSTB, MIF, and KRT19 levels in pancreatic cancer." (PMID 40289610, 2025). "MIF was previously found to recruit TAM to liver pre-metastatic niches and induce fibronectin via TGF in pancreatic cancer." (PMID 37940972, 2023). "Another exosomal marker, macrophage migration inhibitory factor (MIF), has been shown to be related to the chance of liver metastasis in individuals with stage I pancreatic cancer." (PMID 35664698, 2022).
pancreatic cancer (continued). "Over-expression of MIF induced a marked increase of miR-301b and reduction of NR3C2 levels, resulting in profound proliferation, migration, and invasion of pancreatic cancer cell lines (PANC-1 and Capan-2)." (PMID 33776775, 2021). "MIF was found to be expressed at high levels in PDAC-derived exosomes, and genetic ablation of MIF prevented the sequential events involved in liver PMN formation and pancreatic cancer metastasis in mice." (PMID 29903049, 2018). "Several cytokines, such as interleukin-10 (IL-10), macrophage migration inhibitory factor (MIF), and CCL-18, have been shown to induce EMT in pancreatic cancer cells." (PMID 27191744, 2016). "Three cancer‐correlated biomarkers (epidermal growth factor receptor (EGFR), one pancreatic cancer marker (glypican‐1, GPC1) and macrophage migration inhibitory factor (MIF)) can be detected by the developed MAIP‐based platform with a detection limit as low as 5 pg mL−1." (PMID 40598854, 2025). "Macrophage migration inhibitory factor (MIF), enriched in pancreatic tumor exosomes, could impel hepatic Kupffer cells to secrete and release TGF-β." (PMID 39054529, 2024). "The results of this study suggest that MIF of non-cancer cell origin can also promote pancreatic tumor growth." (PMID 31664114, 2019). "In patients whose pancreatic tumours did not progress, MIF was greater in the exosomes of the patients with early stage pancreatic tumours that developed metastasis in the liver." (PMID 28105072, 2016). "Expression level of MIF gene was similar between the group of chronic pancreatitis and non-DM pancreatic cancer." (PMID 24708788, 2014). "The MIF expression was analyzed by western blot and real-time PCR, results showed that stable MIF-over expressing immortalized human pancreatic ductal epithelial cells (HPDE6) and shRNA MIF-knockdown pancreatic cancer cells (PANC-1 and Capan-2) were generated." (PMID 24708788, 2014). "Similarly, serum MIF levels were also higher in new-onset than long term DM-PC, pancreatic cancer without DM, or new-onset T2DM patients (all p < 0.001)." (PMID 33776775, 2021). "Moreover, it has demonstrated that a high level of circulating MIF originating from non-tumor cells might also promote pancreatic tumor growth in vivo." (PMID 31664114, 2019). "Compared with patients without progression of pancreatic tumors, MIF in patients with stage I PC who later developed liver metastasis gained significantly, indicating that exosomal MIF plays an important role in liver metastasis and may be a prognostic marker for predicting liver metastasis." (PMID 31487880, 2019). "Similarly, expression levels of MIF and LRP1 showed significantly negative correlation in 196 pancreatic cancers from TCGA using UCSC Xena database (Pearson’s rho r = -0.3718, P = 2.204e-7)." (PMID 36703790, 2022).